TIGAR (TP53 induced glycolysis regulatory phosphatase)
Diseases named in the same sentence as TIGAR in open-access papers (continued):
Sharing a sentence is not in itself a finding about the gene and the disease.
dementia (5 papers, 2013 to 2026). Loss of intellectual abilities interfering with an individual's social and occupational functions. "Decreased levels of TIGAR protein are found in different stages of Alzheimer’s disease (AD) dementia." (PMID 36437984, 2022). "Taken as whole, the present findings suggest that ATM upregulation and progressive decrease of TIGAR protein levels are distinctive features of dementia progression in AD." (PMID 23861893, 2013). "We additionally report dementia related changes in the expression of TIGAR and show its neuronal localization." (PMID 23861893, 2013). "However, there are several conflicting studies showing expression of TIGAR is inversely correlated with the severity of AD, although in mild dementia, downregulation of TIGAR was noted in the superior temporal cortex." (PMID 35572126, 2022). "As such, inhibition of TIGAR function may also provide a novel approach to improve skeletal muscle function, memory, and dementia through increased cholinergic signaling while limiting the deleterious metabolic consequences secondary to currently available therapies." (PMID 35254259, 2022). "Previous studies on the progression of dementia suggested that reduced TIGAR expression may have a negative impact on cell survival." (PMID 41487468, 2026). "The decrease of TIGAR expression may have a negative impact on cell survival during the progression of dementia." (PMID 36437984, 2022).
chronic lymphocytic leukemia (4 papers, 2013 to 2021).
lymph node metastasis (4 papers, 2013 to 2020). "High TIGAR expression was observed to be significantly correlated with elder age, lymph node metastasis, and advanced AJCC stages of gastric patients." (PMID 31799200, 2019). "The level of TIGAR and Met was positively correlated with lymph node metastasis and distant metastasis, suggesting that TIGAR and Met plays an important role in the metastasis of NSCLC." (PMID 29753331, 2018).
ovarian carcinoma (4 papers, 2019 to 2023). A malignant neoplasm originating from the surface ovarian epithelium. "We show that TIGAR is amplified in several cancer types, and higher expression of TIGAR associates with poor overall survival in ovarian cancer." (PMID 31508509, 2019). "The analysis of datasets from TCGA indicates that TIGAR is amplified across different cancer types including ovarian cancer, in which it is amplified in over 11% of cases." (PMID 31508509, 2019). "To confirm this effect in our ovarian cancer cell lines, we performed senescence-associated β-galactosidase (SA-β-gal) analysis in OVCA420* cells that were transduced with NTC shRNA or three different shRNAs targeting TIGAR." (PMID 31508509, 2019). "The authors find that knockdown of TIGAR increases intracellular reactive oxygen species levels, enhances more DNA damage after olaparib treatment, and induces a state of “BRCAness”, suggesting that TIGAR is a potential therapeutic target in ovarian cancer patients." (PMID 31508509, 2019). "CRISPR-Cas9 screening also identified glycolysis and apoptosis regulator (TIGAR), also known as C12orf5, as a regulator of PARP inhibitors responsiveness in ovarian cancer cells." (PMID 35372044, 2022).
adenoma (3 papers, 2014 to 2021). A neoplasm arising from the epithelium. "The TIGAR protein has antioxidant activity that supports intestinal tissue repair and adenoma development." (PMID 31983610, 2020). "TIGAR is also highly expressed in these adenomas when compared to the surrounding normal tissue, supporting the importance of TIGAR in proliferating tissue." (PMID 24383451, 2014).
Alzheimer disease (3 papers, 2021 to 2026). A progressive, neurodegenerative disease characterized by loss of function and death of nerve cells in several areas of the brain leading to loss of cognitive function such as memory and language. "TIGAR plays an important role in diseases such as cancer, stroke, Alzheimer's disease, Parkinson's disease, chronic lung inflammation, heart failure, and myocardial ischemia, and the recent studies indicated that TIGAR may be a viable therapeutic strategy for obesity." (PMID 41487468, 2026).
hepatocellular carcinoma (3 papers, 2019 to 2024). A malignant tumor that arises from hepatocytes. "The antiproliferative, antimigratory, and proapoptotic effects of dioscin on hepatocellular carcinoma have been related to an inhibition of TIGAR." (PMID 30823646, 2019).
multiple myeloma (3 papers, 2014 to 2021). "In multiple myeloma cells, TIGAR was revealed to be necessary for the maintenance of redox homeostasis, whereas the downregulation of TIGAR resulted in myeloma cell death." (PMID 25621025, 2015). "The role of TIGAR in balancing redox state in cancer cells has also been implicated in multiple myeloma cells, where inhibition of the oncoprotein MUC1-C resulted in a downregulation of TIGAR protein, lower levels of NADPH and in turn, increased ROS and cell death." (PMID 24383451, 2014).
myeloid leukemia (3 papers, 2021 to 2025). A clonal proliferation of myeloid cells and their precursors in the bone marrow, peripheral blood, and spleen. "The previous study conducted by the investigators revealed that TIGAR is highly expressed in myeloid leukemia cell lines and AML primary cells and is associated with the poor prognosis of adult patients with cytogenetically normal AML." (PMID 33532040, 2021). "Our previous study revealed that TIGAR is highly expressed in myeloid leukemia cell lines and AML primary cells and associated with poor prognosis in adult patients with cytogenetically normal AML." (PMID 33532040, 2021). "Research has shown that desitabin downregulates TIGAR, inducing apoptosis and autophagy in myeloid leukemia cells, affecting cell metabolism, apoptosis, and immunity." (PMID 39091612, 2024). "Taken together, DAC plays an unmethylated role in inducing apoptosis and activating autophagy in myeloid leukemia by downregulating TIGAR." (PMID 33532040, 2021). "Taken together, the present study revealed that in addition to hypomethylation, DAC can also play an antitumor role in myeloid leukemia by downregulating the TIGAR and BCR-ABL proteins." (PMID 33532040, 2021). "We have previously reported that TIGAR was highly expressed in several myeloid leukemia cell lines (HL-60, K562, Jurkat, and NB-4), especially in HL-60 cells, but relatively low in K562 cells." (PMID 33532040, 2021). "More studies should be done to discover specific TIGAR inhibitors; hence, the combination of glycolytic inhibitors with TIGAR inhibitors along with the chemotherapeutic agents that are already being used today can be a potential and effective treatment for myeloid leukemia." (PMID 40277923, 2025). "In the present study, it was further confirmed that TIGAR can increase the level of NADPH and decrease the level of ROS in myeloid leukemia cells by silencing or overexpressing TIGAR in HL-60 and K562 cells, respectively." (PMID 33532040, 2021). "Since the function of TIGAR is closely correlated to regulate the cellular redox status, this was a great significance to the study of the expression of TIGAR and its related effects due to DAC treatment in human myeloid leukemia cell lines." (PMID 33532040, 2021). "Therefore, it was speculated that DAC may play an important role in nonmethylation in myeloid leukemia by downregulating the TIGAR gene." (PMID 33532040, 2021).
Sepsis (3 papers, 2024 to 2026). Sepsis is defined as life-threatening organ dysfunction caused by a dysregulated host response to infection. "In this study, we demonstrate that TIGAR expression is markedly reduced in small intestinal crypts of burn sepsis mice." (PMID 41708588, 2026). "Interference with the binding of TIGAR to TAK1 by 5Z-7-oxozeaenol exhibits therapeutic effects in male murine model of sepsis." (PMID 38773142, 2024). "Here the authors show TIGAR drives inflammation and sepsis via activation of TAK1 and that disruption of TIGAR-TAK1 interaction in a murine model of sepsis reduces immunopathology." (PMID 38773142, 2024). "The therapeutic effects of 5Z-7-OX on sepsis may be attributed to its anti-inflammatory properties, which is rooted in preventing the interaction between TIGAR and TAK1." (PMID 38773142, 2024). "We also verified the role of macrophage TIGAR in murine CLP-induced sepsis." (PMID 38773142, 2024). "TIGAR elicits a complex formation with TAK1 and TRAF6 through protein–protein interaction and activation of TAK1, thereby promoting inflammation and accelerating the progression of sepsis." (PMID 38773142, 2024). "Notably, recent studies have shown that TIGAR in macrophages drives inflammation by directly binding to TAK1 and promoting its ubiquitination and autophosphorylation; disrupting the TIGAR-TAK1 interaction significantly alleviates sepsis." (PMID 41584453, 2025).
Stroke (3 papers, 2016 to 2026). Sudden impairment of blood flow to a part of the brain due to occlusion or rupture of an artery to the brain. "The combination of TIGAR and cerebral ischemic preconditioning probably become a new target for stroke prevention and treatment." (PMID 36437984, 2022). "TIGAR can increase the survival rate of stroke animals, improve motor function, and promote the recovery of cognitive function." (PMID 36437984, 2022). "In animal and cellular stroke models, I/R increased mitochondrial localization of TIGAR." (PMID 36437984, 2022). "The combination of TIGAR and cerebral ischemic preconditioning also may be a new target for stroke prevention." (PMID 36437984, 2022). "The combination of TIGAR and cerebral preconditioning may be a new therapeutic target for stroke prevention and treatment." (PMID 27256465, 2016).
cardiac hypertrophy (2 papers, 2024 to 2026). "In contrast, deficiency of TIGAR blunted Ang-II-mediated cardiac hypertrophy." (PMID 38397106, 2024). "This study provides new insights into the role of TIGAR in cardiac metabolism during hypertension to improve cardiac hypertrophy." (PMID 38397106, 2024). "To further investigate the possible molecular mechanism by which ablation of TIGAR attenuates cardiac hypertrophy, we examined the expression of glycolysis-related proteins which are critical factors during the development of cardiac hypertrophy and HF." (PMID 38397106, 2024). "Our study demonstrated a protective role of ablation of TIGAR in Ang-II-induced cardiac hypertrophy." (PMID 38397106, 2024). "Our present study suggests that TIGAR is involved in the control of glucose metabolism and glucose transporters by Ang-II and that knockout of TIGAR attenuates the development of maladaptive cardiac hypertrophy." (PMID 38397106, 2024). "Our present data suggest a fundamental role of TIGAR in cardiac hypertrophy in Ang-II-induced hypertension." (PMID 38397106, 2024). "Our previous study demonstrated that TIGAR played a critical role in myocardial glycolytic function and that the ablation of TIGAR attenuated pressure overload-induced cardiac hypertrophy and dysfunction." (PMID 38397106, 2024). "The present study examined whether TIGAR played a role in chronic Ang-II-induced hypertension, myocardial hypertrophy, and glucose metabolism by using the TIGAR knockout (TIGAR KO) mice." (PMID 38397106, 2024). "However, our data revealed that Ang-II-induced cardiac hypertrophy was significantly reduced in TIGAR KO mice." (PMID 38397106, 2024). "Moreover, in the presence of TIGAR, this led to more profound cardiac hypertrophy due to preferential utilization of glucose for biomass synthesis via the pentose phosphate pathway (PPP) rather than ATP production." (PMID 38397106, 2024). "In addition, knockout of TIGAR attenuated Ang-II-induced maladaptive cardiac hypertrophy, preserving the levels of PFK-1 and Glut-4, and increasing F2,6-BP production." (PMID 38397106, 2024). "Using mice with whole-body and cardiomyocyte-specific TIGAR knockout, we demonstrated remarkable cardioprotection following myocardial infarction with maintained ejection fraction, and complete resistance to diet-induced cardiac hypertrophy despite comparable weight gain." (PMID 41746736, 2026). "However, the knockout of TIGAR significantly attenuated hypertension-induced cardiac hypertrophy." (PMID 38397106, 2024). "The results demonstrate that knockout of TIGAR in mice increased levels of F2,6-BP, upregulated PFK1, and attenuated myocardial hypertrophy but had little effect on blood pressure, cardiac dysfunction, and fibrosis." (PMID 38397106, 2024). "Interestingly, knockout of TIGAR significantly reduced LV mass compared to the WT mice + Ang-II group, suggesting that TIGAR-mediated glycolysis may play a role in Ang-II-induced cardiac hypertrophy." (PMID 38397106, 2024).
diabetes (2 papers, 2019 to 2023). "However, under hyperglycemic conditions, the effect of TIGAR on diabetes-induced neuronal autophagy impairment is still unclear." (PMID 31456661, 2019).
diabetic cardiomyopathy (2 papers, 2021 to 2023). Diabetic cardiomyopathy is a disorder of the heart muscle in people with diabetes.
heart failure (2 papers, 2024 to 2026). Inability of the heart to pump blood at an adequate rate to meet tissue metabolic requirements. "We have demonstrated that TIGAR deficiency reduced endothelial inflammatory activation and attenuated TGF-β signaling and myocardial fibrosis after pressure overload-induced heart failure." (PMID 38397106, 2024).
Hyperglycemia (2 papers, 2019 to 2023). An increased concentration of glucose in the blood. "TIGAR is highly expressed in neurons, but its role in hyperglycemia-induced neuronal injury is still unclear." (PMID 31456661, 2019). "In the present study, we focus on the significance of TIGAR on neuronal glucose metabolism and provide several new insights into the effect of TIGAR on hyperglycemia-induced neuronal apoptosis." (PMID 31456661, 2019). "In this study, we aimed to investigate the effect of TIGAR in hyperglycemia-induced neuronal apoptosis and autophagy impairment." (PMID 31456661, 2019). "Overexpression of TIGAR protected hyperglycemia-induced neuronal apoptosis." (PMID 31456661, 2019). "Our work revealed a novel mechanism linking the glycolysis regulator TIGAR with neuronal apoptosis in hyperglycemia conditions and indicated that TIGAR might prevent neuronal apoptosis via regulation of the autophagy process." (PMID 31456661, 2019). "However, the effect of TIGAR in hyperglycemia-induced neuronal apoptosis remains elusive." (PMID 31456661, 2019).
Hypertension (2 papers, 2022 to 2024). The presence of chronic increased pressure in the systemic arterial system. "Taken together, chronic TIGAR deficiency associated increase in glycolysis and pro‐fibrotic signaling during Ang‐II infusion‐induced hypertension contribute to the development of renal interstitial fibrosis." (PMID 35441828, 2022). "In the present study, we investigated the role of TIGAR in cardiac remodeling during Angiotensin II (Ang-II)-induced hypertension." (PMID 38397106, 2024). "In the present study, we investigated the role of TIGAR in renal glycolysis, fibrosis, and glomerular injury during Ang‐II‐induced hypertension." (PMID 35441828, 2022). "Our present data suggest a fundamental role of TIGAR in renal glycolysis and the development of fibrosis and glomerular injury in Ang‐II‐induced hypertension." (PMID 35441828, 2022). "This study provides new insights into the role of TIGAR in renal metabolism and pathological remodeling during Ang‐II‐induced hypertension." (PMID 35441828, 2022). "In the present study, we assessed the effect of ablation of TIGAR in renal function, metabolism, interstitial fibrosis, and glomerular injury during Ang‐II‐induced hypertension." (PMID 35441828, 2022). "We further examined the role of TIGAR in diastolic function in Ang-II-induced hypertension." (PMID 38397106, 2024). "In the present study, the blood pressure was not different between the WT and TIGAR KO mice, suggesting that TIGAR is not involved in regulating Ang-II-induced hypertension." (PMID 38397106, 2024). "At present, the role of TIGAR in modulating glucose metabolism in hypertension-induced HF has not been studied." (PMID 38397106, 2024).